NGF (nerve growth factor)
Diseases named in the same sentence as NGF in open-access papers (continued):
Sharing a sentence is not in itself a finding about the gene and the disease.
diabetes (continued). "Diabetes-induced imbalance of proNGF/NGF resulted in upregulation of proNGF/p75NTR axis and downregulation of NGF/TrkA axis." (PMID 26807305, 2015). "The results of this pilot study shed light on the relationship between the diabetes-induced proNGF/NGF imbalance in vitreous and serum." (PMID 25853140, 2015). "Diabetes alters the homeostasis of NGF by favoring accumulation of proNGF at the expense of the mature NGF." (PMID 26807305, 2015). "During diabetes, the imbalance of proNGF/NGF expression favors proNGF/p75NTR pathway, which has been linked to retinal inflammation, and apoptosis." (PMID 26807305, 2015). "We demonstrated that diabetes disturbs the homeostasis of nerve growth factor (NGF) resulting in accumulation of its precursor proNGF." (PMID 23998130, 2013). "Our studies showed that diabetes-induced peroxynitrite formation impairs maturation of NGF, leading to accumulation of its precursor proNGF both in experimental models and in clinical diabetes." (PMID 23998130, 2013). "Impaired balance of proNGF and NGF was involved in neurovascular injury in diabetes, and abnormal upregulation of proNGF, p75NTR and sortilin was also associated with retrovirus-induced spongiform encephalomyelopathy." (PMID 24040063, 2013). "EA represents a supportive tool to control DPN development by modulating NGF signaling in diabetes-targeted neurons." (PMID 23710226, 2013). "NGF overexpression is widely observed in cardiac pathologies (MI, diabetes, etc.)and more likely plays a beneficial role in cardiac cells survival and heart function." (PMID 24244423, 2013). "Several reports have documented increases in NGF levels in serum from patients with insulin-dependent diabetes mellitus and in serum and tears from patients with diabetic neuropathy and retinopathy." (PMID 23358247, 2013). "It was also demonstrated that diabetes-induced peroxynitrite mediates retinal neurodegeneration by inhibiting NGF survival signaling." (PMID 23762379, 2013). "Our previous analyses showed that diabetes-induced oxidative stress disturbs the homeostasis of NGF by hampering the cleavage of proNGF resulting in accumulation of proNGF and reducing NGF levels in experimental and ocular fluids from PDR patients." (PMID 23998130, 2013). "The early (4 weeks long) experimental diabetes is characterized by an increased NGF availability for the DRGs sensory neurons, concomitant with increased protein contents of NGF receptors TrkA and p75NTR, and by increased TrkA phosphorylation." (PMID 23710226, 2013). "Here, we investigated the possible regulation of the NGF system in primary sensory neurons and in their innervation targets, in the early phase of experimental diabetes after EA treatment." (PMID 23710226, 2013). "Deficits of NGF transport, serum and tissue content have been demonstrated in experimental diabetes." (PMID 23190582, 2012). "The decreased nerve regenerative capacity in diabetes has been associated with impaired neurotrophic tone, which could reflect diminished synthesis, secretion or responsiveness of neurotrophic factors such as NGF and structural protein in sensory and autonomic nerve fibers." (PMID 20871761, 2010). "For example, the NGF derivative R100E could facilitate the healing of nerve endings and skin lesions in individuals with diabetes." (PMID 40783715, 2025). "Beyond neuropathy, NGF has been tested for male reproductive and sexual outcomes in diabetes." (PMID 41471293, 2025). "Thus, to investigate the effect of NGF in the Akt-FoxO1 signaling pathway in obese- and diabetes-induced muscle atrophy, the phosphorylation of Akt was evaluated in the gastrocnemius muscle tissues." (PMID 38673892, 2024). "However, it should be emphasized that the observed decrease in NGF levels in the course of diabetes cannot be clearly interpreted." (PMID 36983153, 2023).
diabetes (continued). "However, both Rilmenidine-treated groups showed increased NGF levels: the diabetes + 0.1 mg/kg Rilmenidine group (56.4 ± 1.5 pg/mg) and the diabetes + 0.2 mg/kg Rilmenidine group (60.8 ± 4.06 pg/mg)." (PMID 38055406, 2023). "This suggests that NGF levels increase at early stages and decrease at later stages of diabetes and that they could relate to beta cell functions." (PMID 36768281, 2023). "Paradoxically, db/db mice show increased plasma NGF levels during the early stages of diabetes." (PMID 36768281, 2023). "A recent study has shown a positive correlation between 25(OH)D and serum NGF in diabetes patients." (PMID 36359415, 2022). "Exogenous NGF has been shown to alleviate diabetic neuropathic pain." (PMID 35127954, 2022). "In addition, the pre-diabetes elderly were found to have increased NGF, BDNF, and cathepsin B, and decreased Beta-Amyloid 1–42 and homocysteine." (PMID 35455914, 2022). "Overall, these results indicate that electroconductive a-MWCNTs 2 could possibly stimulate a neuro-reparative mechanism in a diabetic brain, based on the stimulation of NGF neurotrophic activity." (PMID 36131737, 2021). "Similarly, we detected a decrease in the cellularity of islets of Langerhans for the female and male rats in the diabetes group, a significant decrease in the NGF immunoreactivity and total disappearance of Trk-A immunoreactivity." (PMID 34174790, 2021). "Our results suggested that the cinnamon led to an increase in the NGF immunoreactivity in the islet cells and the NGF might have a role in the regulation of blood glucose in the diabetes." (PMID 34174790, 2021). "Moreover, the levels of NGF mRNA and protein are increased in several human pain disorders, especially in the context of inflammation as in diabetes." (PMID 33927613, 2021). "Local application of NGF exerts a healing action on corneal and cutaneous ulcers associated with pathological conditions such as inflammation, diabetes and rheumatoid arthritis, and the use of NGF as a drug in ophthalmology is the best characterized and developed clinical use of this neurotrophin." (PMID 34335170, 2021). "Our group demonstrated in vitro that NGF action is directed at the main cell types involved in wound healing (keratinocytes, fibroblasts, and endothelial cells), as well as at hyperglycemic conditions which mimic the pathological microenvironment of diabetes." (PMID 34335170, 2021). "In this study, we investigated the analgesic effect of the combination of B1/B6/B12 (VBC) and its effects on the expression of P2X3 and TRPV1 receptors in DRG neurons and the inflammatory cytokines IL-1β, TNF-α, and NGF in the spinal cord in STZ-induced diabetic rats." (PMID 32104520, 2020). "Genistein also reduced NGF, oxidative stress, inflammation, and nociceptive hypersensitivity in a time- and dose-dependent manner, and vascular dysfunction that follow streptozotocin induced diabetes in mice." (PMID 32536874, 2020). "Therefore, it is likely that the therapeutic effect is also attributable to preventive actions of NGF, one of which is protection against diabetes-induced bone marrow neuropathy." (PMID 31016359, 2019). "In addition, CARB increased pTrKA/TrKA ratio and ameliorated diabetes-induced reduction of NGF mRNA and immunostaining in retina." (PMID 31736682, 2019). "Interestingly, NGF gene therapy prevented the reductive effect of diabetes on PGP9.5- and substance P-positive fibre density (p < 0.05 vs βGal mice for both comparisons)." (PMID 31016359, 2019). "NGF is involved in modulating the sensitivity of peripheral nerve fibers to heat and pain in physiological and pathological events, such as genetic, metabolic (diabetes mellitus), and infectious neuropathies." (PMID 29867937, 2018). "In this regard, we aim to investigate the role of the NGF/TrkA signaling pathway in diabetic ED." (PMID 29285284, 2017).
diabetes (continued). "Exogenously applied neurotrophic factors, growth factors, and other biological molecules improved axonal regeneration and other neurological functions in animal models of diabetes; however, the translation of these molecules (e.g., NGF, BDNF, and VEGF) to humans has failed in clinical trials." (PMID 28203223, 2017). "Furthermore, tadalafil enhanced diabetes-reduced nerve growth factor (NGF) and platelet-derived growth factor-C (PDGF-C) protein levels in diabetic sciatic nerve tissue." (PMID 27438594, 2016). "Recent work showed that NGF supplementation reduced RGC death in diabetes and glaucoma rat model." (PMID 26807305, 2015). "Our previous studies have demonstrated that diabetes-induced oxidative stress alters homeostasis of retinal nerve growth factor (NGF) resulting in accumulation of its precursor, proNGF, at the expense of NGF which plays a critical role in preserving neuronal and retinal function." (PMID 25853140, 2015). "In RGCs, a cell line of immortalized retinal ganglion cells that express NGF and its receptors, TrkA and p75NTR, diabetes-induced peroxynitrite formation has been shown to impair TrkA receptor phosphorylation and activate the p75NTR-dependent proapoptotic pathway, leading to neuronal cell death." (PMID 25688355, 2015). "Diabetes-induced proNGF expression and impaired NGF expression were observed in vitreous and serum." (PMID 25853140, 2015). "Similarly, genetic deletion of p75NTR reversed diabetes-induced imbalance of proNGF/NGF by decreasing proNGF and restoring NGF levels." (PMID 26807305, 2015). "In diabetes, an impaired production of matrix metalloproteinase-7, which cleaves the NGF precursor proNGF, has been observed, leading to the decrease in NGF and to the accumulation of proNGF, which binds to p75NTR and preferentially activates a proapoptotic pathway." (PMID 25688355, 2015). "Similarly, diabetes increased serum and kidney levels of NGF in an experimental model of diabetic nephropathy." (PMID 26807305, 2015). "RGC apoptosis has been quantified upon chemical NGF deprivation, while the recovery of damaged structures and particularly NGF/trkANGFR-promoted RGC survival were observed upon the intraocular NGF injection, as observed in models of retinal degeneration (ischemia, glaucoma, and diabetes)." (PMID 24627687, 2014). "This activity may be beneficial in vivo, as NGF gene therapy is cardioprotective in models of myocardial infarction and diabetes." (PMID 23437390, 2013). "The normalization of NGF signaling by EA in early diabetes could also be of neuroprotective relevance to DRG neurons." (PMID 23710226, 2013). "In addition to these known growth factors, recent findings using ocular fluids from diabetic patients and experimental models of diabetes suggest that neurotrophins including nerve growth factor (NGF) are emerging as critical mediators of DR." (PMID 23998130, 2013). "Our previous studies have shown that diabetes-induced oxidative stress disturbs the homeostasis of nerve growth factor (NGF) resulting in accumulation of its precursor proNGF at the expense of the mature NGF in diabetic rat and ocular fluids from diabetic patients." (PMID 23998130, 2013). "In conclusion, NGF-triggered DRG neuron hyperactivity could be of primary importance in the establishment of DPN and in the early diabetes-associated neuronal distress." (PMID 23710226, 2013). "EA could revert neuropathic symptoms in the early diabetes, and its action is possibly exerted on mediators of DRGs neuron sensitization, such as NGF, MAPKs, and the TRPV1." (PMID 23710226, 2013). "Thus, neuroprotective effect of various neurotrophic or NGF mimetic agents on diabetes had been tested." (PMID 23671883, 2013). "However, several reports documented paradoxical increases in NGF levels in the serum of patients with insulin-dependent diabetes mellitus and in the serum and tears of patients with diabetic neuropathy and retinopathy." (PMID 21293735, 2011).
diabetes (continued). "NGF and structural proteins are required not only for the development and regeneration but also for the maintenance of sensory and autonomic neurons and their axons, which serve as biomarkers of neuropathy in animal models of diabetes." (PMID 20871761, 2010). "Knowing the roles of NGF in pancreatic islet development, maturation, innervation and function may lead us to new perspectives for understanding and treatment of diabetes mellitus, including better conditions of islets for transplantation." (PMID 19534767, 2009). "Furthermore, circulating levels of IGFs and NGF are reduced in diabetes and to a greater degree in patients with thermal sensory deficits characteristic of neuropathy." (PMID 15857517, 2005). "Hence, the intrathecal delivery of NGF enhances the analgesic effect of fentanyl on diabetes-related hyperalgesia, which could explain why anti-NGF mAbs exhibit limited antinociceptive effects." (PMID 40783715, 2025). "In addition to its influence on NGF, diabetes might affect CGRP+ sensory nerves by directly influencing sensory neurons in the trigeminal ganglia." (PMID 40755317, 2025). "In addition, NGF has been reported to antagonize molecular alterations downstream of insulin resistance receptors, suggesting new potential therapeutic targets to slow diabetes-related brain insulin resistance." (PMID 36675322, 2023). "Moreover, the recovery of brain vascular alterations has been found in animal models, including diabetes, suggesting that the crosstalk between NGF and VEGFA might participate in retinal cell survival." (PMID 36291113, 2022). "Furthermore, the upregulated P0 and NGF protein expression demonstrated by immunohistological staining reconfirmed the neuroprotective effects of SalA on peripheral neuropathy induced by diabetes." (PMID 32184918, 2020). "To investigate whether NGF gene therapy prevents bone marrow sensory neuropathy, we delivered an Ad.hNGF construct, described previously, to mice intravenously, 2 weeks after induction of diabetes by STZ." (PMID 31016359, 2019). "A combination of the reported data demonstrates that NGF could be used inpatients with type 2 diabetes mellitus because of its ability to maintainβ-cell function, stimulate insulin secretion, and simultaneously impedethe development of diabetes mellitus and its comorbidities." (PMID 28740732, 2017). "The present study showed that diabetes reduced NGF and PDGF-C proteins in Schwann cells of the sciatic nerve tissue, whereas tadalafil treatment increased these two proteins, suggesting that NGF and PDGF-C may be involved in processes of diabetic peripheral neuropathy." (PMID 27438594, 2016). "Thus, diabetes-induced alterations in the proNGF/NGF imbalance in serum may well reflect combined contributions from the retina, other organs, the immune system, and the vasculature." (PMID 25853140, 2015). "Previous studies have reported that there is a deficiency of NGF in diabetes, which is compatible with the current finding of decreased bladder NGF level in our DM rats." (PMID 25050870, 2014). "The increases in NGF levels positively correlated with the DR stage and other diabetes mellitus (DM) parameters." (PMID 23358247, 2013). "Our analysis also showed that phloridzin specifically restored pathways regulated by interleukin-1 beta and nerve growth factor, the receptors for which and themselves are expressed by retinal glial cells, once more pointing out the role of Müller cells in the effects of phloridzin on diabetes." (PMID 22046295, 2011). "The increases of NGF levels positively correlated with the diabetic retinopathy stage and other diabetes mellitus (DM) parameters." (PMID 21293735, 2011). "In the STZ-induced diabetes model, ghrelin reduces astrocytic GFAP immunoreactivity in the rat brain and maintains the balance between pro-NGF and NGF, thereby protecting hippocampal neurons." (PMID 39995985, 2025).
diabetes (continued). "It is reported that the expression level of nerve growth factor (NGF), a crucial factor in neuronal maintenance and survival, was significantly reduced in diabetes patients." (PMID 39280583, 2024). "The results indicated that age, diabetes, pelvic inflammation, and the expression of CD117, P2X3R, NGF, TrkA, ESR, and PCT were significantly correlated with IC prognosis (all P < 0.05)." (PMID 38098081, 2023). "Among subjects with diabetes, those with TIR ≤ 70% had higher levels of IL-1α, IL-1β, IL-6, IL-12 p70, IL-16, LIF, M-CSF, MCP-1, MCP-3, RANTES, TNF-α, TNF-β, and b-NGF, and lower levels of IL-1α, IL-4, IL-10, GM-CSF, and MIF than individuals with TIR > 70%." (PMID 37893217, 2023). "The discovery that rat and human beta cells synthesize and secrete NGF, along with the notion that NGF regulates GSIS, fueled ideas about the possible roles of this factor during the pathogenesis of MS and diabetes mellitus (DM)." (PMID 36768281, 2023). "Vildagliptin reversed diabetes-induced decrease of p-Akt, p-GSK-3β, brain-derived neurotrophic factor and nerve growth factor, thus against cognitive deficits and memory impairment." (PMID 31237881, 2019). "After incubation with CpG B and LCMV gp33–41 peptide in the absence or presence of NGF, WT pDCs were transplanted into heterozygous RIP-CD80GP mice and the development of diabetes was determined by consecutive blood glucose measurement." (PMID 28861085, 2017). "Diabetes also decreases the anterograde and retrograde axonal transport of BDNF, NGF, and NT-3 in peripheral nerves." (PMID 28900628, 2017). "Our group has discovered that diabetes causes an imbalance of increased proNGF at the expense of mature NGF due to impaired MMP-7 activity in clinical and experimental diabetes." (PMID 25853140, 2015). "Increases in proNGF and decreases in NGF in vitreous from PDR patients lend further support to our previous findings in ocular fluids of diabetic patients and experimental diabetes." (PMID 25853140, 2015). "Nerve growth factor (NGF) is essential for the development and functional maintenance of dorsal root ganglion (DRG) sensory neurons, which are primarily targeted by diabetes, and has been indicated as a possible therapeutic for peripheral neuropathies." (PMID 23710226, 2013). "Previous studies have shown that activation of pro-NGF/P75NTR signaling contributes to retinal neuronal damage in animal models of glaucoma, retinal degenerations and diabetes." (PMID 24224958, 2013). "The pTyr496-TrkA, the activated form of TrkA, was significantly increased by diabetes (STZ versus controls: +54%, P < 0.05), indicating an augmented NGF signaling." (PMID 23710226, 2013). "Our recent studies demonstrated significant and progressive increases in levels of proNGF at the expense of NGF in human samples from diabetic patients, PDR patients, and experimental diabetes." (PMID 21293735, 2011). "Taken together, these results indicate that although NGF expression is not influenced by diabetes, the neural microenvironment is impaired by this systemic disease." (PMID 40755317, 2025). "In the present study, we examined the expression levels of NGF and Sirt1 in human pancreatic tissue specimens and found that they were lower in islet β cells in patients with diabetes than in those without and inversely correlated with insulin secretion." (PMID 41181709, 2025). "For the four week group, BIC increased 55.46% for the non-diabetic group, 42.61% for the diabetes group, and 54.34% for the group with NGF administration." (PMID 36995883, 2023). "Meanwhile, for the six week group the average BIC was 65.44% for the non-diabetic group, 55.75% for the diabetes group, and 67.99% for the group receiving NGF." (PMID 36995883, 2023). "Type 1 diabetes mellitus patients who have no complications exhibit higher serum NGF levels when compared to non-diabetics." (PMID 37373824, 2023).